PPARG (peroxisome proliferator activated receptor gamma)
Diseases named in the same sentence as PPARG in open-access papers (continued):
Sharing a sentence is not in itself a finding about the gene and the disease.
tumor (continued). "Moreover, in view of the tumor suppressor function of Par-4, its inverse relationship with PPARγ, and abnormal lipid metabolism caused by increased PPARγ expression in cancer, it will be important to determine the functional significance of the inverse relationship between Par-4 and PPARγ in cancer." (PMID 39273065, 2024). "Here, we propose for the first time that targeting PPARγ can link these two death pathways to inhibit tumor cell proliferation." (PMID 38786003, 2024). "For example, thiazolidinediones-activated PPARγ is able to arrest tumor angiogenesis and in vivo cell growth in ovarian carcinoma and pancreatic cancer." (PMID 39199386, 2024). "In the pulmonary metastasis cohort instead, a trend towards longer survival was observed for patients with high PPARG expression in their tumour (p = 0.059)." (PMID 38378472, 2024). "Another study proposed that the upregulation of PPARG has been demonstrated to enhance the chemosensitivity of HSCC tumor cells by influencing both cell proliferation and cell motility pathways." (PMID 38505269, 2024). "Itaconate downregulates peroxisome proliferator-activated receptor gamma as a tumor-suppressing factor and upregulates anti-inflammatory cytokines in M2-like macrophages." (PMID 38611081, 2024). "Several studies in mice and humans show that PPARγ prevents tumor initiation and progression, acting as a tumor suppressor gene." (PMID 39199386, 2024). "Nevertheless, with respect to anti-tumor immunity, PPARγ-induced dendritic cell ferroptosis damages cell maturation and tumor suppression." (PMID 38961066, 2024). "PPARγ has been identified as a tumor‐suppressor gene in hepatocarcinogenesis, exerting its inhibitory effects on tumor cell growth through mechanisms such as suppression of cell proliferation, induction of G2/M arrest, and promotion of apoptosis." (PMID 39126216, 2024). "For instance, PPARα and PPARγ mainly act as a tumor suppressor and a promoter, respectively, during tumor progression, whereas PPARβ/δ plays a controversial role in tumorigenesis." (PMID 39519311, 2024). "Both for in vitro and in vivo peroxisome proliferator-activated receptor gamma (PPARγ) with its function in tumor suppressing can transactivate genes for β-oxidation." (PMID 38841622, 2024). "The role of PPARG is widely debated and it exerts inhibitory or promotional effects on cancer growth depending on the tumor cell conditions and the pathways stimulated." (PMID 39654890, 2024). "For instance, ligands acting as PPARγ agonists can inhibit tumor development by activating PPARγ and forming biomolecular condensates with co-activators." (PMID 38383403, 2024). "Currently, PPARγ receptor antagonists have been found in various cancer studies to inactivate PPARγ to regulate tumor occurrence and development." (PMID 38786003, 2024). "VDR and PPARγ signaling play roles to regulate inflammation which is of importance to the tumor microenvironment." (PMID 39273194, 2024). "In conclusion, these data provide strong evidence that PPARγ and possibly PPARα represent key tumor suppressors by acting as master inhibitors of the inflammatory changes found in AKs and SCCs." (PMID 39195246, 2024). "Thiazolidinediones have been found to inhibit cancer cell behaviour in various tumour cells via PPARγ‐dependent and PPARγ‐independent mechanisms, such as a decrease of metalloproteinase 2 (MMP2) activity." (PMID 39636301, 2024). "NMIBC is more frequently classified as a luminal subtype, in which increased PPARγ activity is a key feature in promoting tumor growth and evasion of immunosurveillance." (PMID 39695138, 2024). "At first, PPARγ was viewed as a tumor suppressor for PCa; agonists were shown to inhibit PCa cell growth, but this was then found to be PPARγ independent." (PMID 39273194, 2024). "It has been reported that PPARG holds a potential action in dedifferentiated LPS and acts as a tumor suppressor in many tumors." (PMID 39063036, 2024).
tumor (continued). "The induction of PPARγ by bitter melon oil (BMO) (Momordica charantia) was also found to suppress tumor growth in a rat model." (PMID 38372868, 2024). "Collectively, these data indicate a potential tumor suppressor role of PPARγ that is mediated by its effects on inflammation and anti-tumor immune responses." (PMID 39195246, 2024). "When the pathway was blocked with PPARγ inhibitors, tumor epithelial cell proliferation was significantly inhibited, and apoptosis increased." (PMID 39687628, 2024). "By innovatively targeting PPARG, it affected osteoclast proliferation and thus affected tumor progression; this work offered new insights and directions for the clinical treatment of OS patients." (PMID 39936154, 2024). "Tumours with high PPARG expression showed an inverse correlation with a 5-FU resistance score and the expression levels of genes associated with 5-FU resistance." (PMID 38378472, 2024). "PPARγ agonists such as ciglitazone, rosiglitazone, and thiazolidinediones inhibit tumor growth, angiogenesis, and metastasis." (PMID 39770941, 2024). "Our study implies that higher PPARγ is consistent with higher tumor growth reflected by the larger size." (PMID 38882990, 2024). "Mechanistically, VEGF-A expressed by tumor cells through activation of peroxisome proliferator-activated receptor-gamma (PPARγ) stimulates MDSC expansion to suppress CD8+ T cell function." (PMID 38397901, 2024). "In comparison to the M0 cohort, patients with isolated lung metastasis (PUL) showed significantly higher PPARG expression in their tumours (p = 0.019)." (PMID 38378472, 2024). "Treatment with RXRs agonists, such as bexarotene, inhibits tumor angiogenesis, suppresses the proliferation and migration of lung tumor cells, and promotes tumor cell death through the PPARγ, PTEN, and mTOR pathways." (PMID 39311119, 2024). "PPARγ is the most extensively studied subtype, and its aberrantly high expression in HCC is associated with metabolic dysregulation and tumour progression." (PMID 38652093, 2024). "One study posits that the mechanism for this involves HPV16 E7 inhibiting PPARγ expression via an increase in miR-27b to facilitate tumour proliferation." (PMID 38474047, 2024). "In line with the in vitro results, ZBTB16 and PPARγ, RXRα protein levels were both increased, which confirmed that PPI effectively inhibits tumor growth by targeting ZBTB16 to activate the PPARγ/RXRα signaling pathway." (PMID 39182119, 2024). "Recent studies have demonstrated that combining radiation with natural compound–based PPARγ agonists is a powerful strategy to sensitize radioresistant tumor cells." (PMID 39770941, 2024). "Histologically, the PPARγ IHC expression in the tumor was cytoplasmic with few scattered cells showing nucleocytoplasmic expression." (PMID 38882990, 2024). "Reportedly, nonsteroidal anti-inflammatory drug inhibition of β-catenin in tumor cells needs elevated expression of PPARγ." (PMID 39272080, 2024). "Patients without distant metastases had a significantly longer overall survival with low PPARG expression in their tumours compared to patients with high PPARG expression (p = 0.045)." (PMID 38378472, 2024).
tumor (continued). "c-Myc directly regulates and replaces activation related genes, upregulates signaling mediators involved in IL4, and transcriptional activators STAS6 and PPARγ involved in the expression of tumor related macrophages." (PMID 39620221, 2024). "With regard to this, combined treatment of indomethacin with 5-FU significantly reduced tumor growth by activating PPARγ and suppressing the expression of PROM 1, CD44, PTGS2, and HES1 in SW620 xenograft mice." (PMID 38372868, 2024). "In DC2.4 cells, the ferroptosis inducer RSL3 can activate the PPARG/PPARγ pathway involved in lipid metabolism to induce ferroptosis, thereby impairs DC maturation and limits anti-tumor immunity." (PMID 39359721, 2024). "In the literature, PPARG is an oncogene, which exerts anti-tumour effects by inhibiting cell proliferation, differentiation, cell growth, cell cycle, and inducing apoptosis." (PMID 39654890, 2024). "In this experiment, control populations dramatically enhanced MCF10DCIS.com tumor size, whereas PPARγ overexpressing populations led to the formation of tumors comparable in size to mice injected with MCF10DCIS.com alone." (PMID 37816052, 2023). "There is a suggestion that PPARG has the potential to enhance the chemosensitivity of HSCC tumor cells." (PMID 37791141, 2023). "Ligand of PPARγ not only improves insulin resistance and blood lipid, immune regulation and anti-inflammation, but also induce anti-tumor cell proliferation and promotes cell differentiation." (PMID 37791070, 2023). "In contrast, lactic acid in the tumor microenvironment lowered PPARγ levels in iNKT cells, abrogating IFNγ production." (PMID 37686465, 2023). "Instead, PPARγ/RXRα knockdown or pharmacological inhibition restored pro-inflammatory cytokine production, alluding to a tumor-specific role of this NHR warranting the careful choice of agonists vs. antagonists to achieve clinical benefit." (PMID 37686465, 2023). "Both preclinical and clinical studies have reported the anticancer effects of PPARγ agonists, including inhibition of tumor growth and reduced angiogenesis." (PMID 38044948, 2023). "The median PPARG gene expression in normal tissue was 1230 (Q1: 882, Q3: 1752) compared to 807.5 (Q1: 481, Q3:1271) in tumour tissue and 635 (Q1: 397.5, Q3: 970) in metastatic tissue (p = 1.06 × 10−28, Kruskal–Wallis test)." (PMID 36835258, 2023). "Pioglitazone, both the PPARα and PPARγ agonistic component, inhibit carcinogenesis, tumor progression, proliferative capacity of metastasis-initiating stem cells, migration, invasion and remodel the extracellular matrix and angiogenesis." (PMID 38273846, 2023). "We also demonstrated that PPARγ suppressed the transition of pericytes toward a myofibroblast-like phenotype capable of supporting tumor cell growth and angiogenesis in vitro and in vivo." (PMID 37816052, 2023). "PPARγ agonist (pioglitazone) restored IFNγ production in tumor-infiltrating iNKT cells from patients and mice, and in combination with an immunostimulant (α-galactosylceramide), enforced iNKT cell-driven anti-tumor responses for prolonged animal survival." (PMID 37686465, 2023). "The importance of PPARγ expression in tumor cells for tumor pathophysiology is determined by the expression of the PPARγ receptor which varies dependent on tumor stage and histology n." (PMID 38273846, 2023). "Previously, PPARγ agonist was observed to induce mitochondria mediated apoptosis in tumor cells and reduce MMP in cancer cells." (PMID 36875279, 2023). "Consistent with our in vitro data, we found that tumor samples from PPARG KO mice had lower pAKT expression than did tumors from WT mice." (PMID 37100807, 2023). "PPARγ functions as a tumor-suppressive factor via PPARγ/RXRα signaling pathway in several tumor types." (PMID 37976136, 2023). "The role of PPARG in HCC patients has been found to suppress tumor growth, angiogenesis, and migration." (PMID 38143739, 2023).
tumor (continued). "A study uncovered that PPARγ stimulated anti-tumor immunity under GM-CSF-secreting tumor cell vaccines." (PMID 37686465, 2023). "Although there is substantial evidence that PPARγ acts as a tumor suppressor and inhibits tumor cell growth in a variety of cancers, its pro-tumor potential should not be overlooked." (PMID 36998980, 2023). "In r/r metastatic melanoma significant improved PFS was observed for patients with high PPARγ expression in respective tumor probes." (PMID 38273846, 2023). "PPARG expression was significantly decreased in tumours compared to normal but increased compared to metastatic colon tissue (post hoc Dunn test, p = 4.35 × 10−26 and p = 1.14 × 10−16, respectively)." (PMID 36835258, 2023). "In a previously published scRNA-seq analysis, PPARγ target genes were among the most down-regulated genes in ECs recovered from normal adjacent and tumor regions." (PMID 37816052, 2023). "Tumor-derived growth factors and cytokines suppressed PPARγ in adipocytes, capillary ECs, and pericytes." (PMID 37816052, 2023). "First, we found that PPARG was downregulated in BC and its expression level correlates with pathological tumor stage (pT-stage) and pathological tumor-node-metastasis stage (pTNM-stage) in BC." (PMID 37334066, 2023). "Recent studies show that increased IL-33 expression in colon cancer cells promotes PPARγ expression in ILC2s, leading to IL-13 release and facilitating tumor migration." (PMID 37686309, 2023). "PTHrP is also secreted by tumor cells and inhibits adipocyte differentiation through peroxisome proliferator-activated receptor gamma (PPARγ) activity inhibition via a mitogen-activated protein kinase (MAPK)-dependent pathway." (PMID 37217930, 2023). "Rostiglitazone, the PPARγ agonist, induced the expression of cytokines, chemokines, and angiogenesis-stimulating factors modifying the tumor microenvironment to favor metastasis." (PMID 36834531, 2023). "PPARγ was considered a tumor suppressor in prostate cells; conversely, new research has found that PPARγ antagonists inhibit cell growth." (PMID 37894275, 2023). "Telmisartan is an ARB clinically indicated for hypertension therapy and has also proved to have anti-cancer effects by activating PPARγ, which halts tumor metastases." (PMID 36661704, 2023). "Restoring the expression of tumor suppressors, such as PTEN with PPARγ agonists attenuates tumor repopulation, prevents residual tumor cells and aggressivity of tumor cells." (PMID 38273846, 2023). "Clinical data and mouse tumor models showed that high PPARγ/RXRαS427F/Y positivity predicts low infiltration of CD8+ T-cells and imposes resistance to immunotherapies." (PMID 37686465, 2023). "A previous study reported that DHA-PC and EPA-PC significantly inhibited orthotopic tumor growth and lung metastasis, via the activation of PPARγ and the downregulation of the NF-κB pathway to control tumor growth and metastasis." (PMID 36902523, 2023). "KLF4 is a Yamanaka factor important for pluripotency, while SMAD3 is essential for TGFB1 signaling, and PPARG has complex roles in tumor metabolism and immunity; they have known roles as positive and negative regulators of EMT and bladder carcinogenesis." (PMID 38129585, 2023). "The increased level of LPE in the Arf1-deficient tumor cells sequestrated PPARγ from the PPARγ-NF-κB complex, which freed NF-κB for regulating CCL5 and T-cell tumor infiltration." (PMID 39872623, 2023). "Peroxisome proliferator-activated receptor gamma (PPARG) can regulate the production of adipocyte-related genes and has anti-inflammatory and anti-tumor effects." (PMID 37334066, 2023). "PPARγ is selectively expressed in group 2 innate lymphoid cells (ILC2s) supported the IL-33-dependent tumor promoting effect." (PMID 36816914, 2023).
tumor (continued). "For example, in this study, two tumor-specific editing sites in PPARG, chr3:12404457 and chr3:12432364, were identified with positive selection." (PMID 36895481, 2023). "The results of an in vitro tumor spheroidization assay showed that the PPARγ antagonists GW9662 and T0070907 reduced tumor spheroids formation in ERBB2-positive cells." (PMID 37251321, 2023). "We observed a 50% reduction in tumor weight and in the number of tumor nodules in the PPARG KO mice compared with WT mice." (PMID 37100807, 2023). "These prostaglandins are inhibitors of nuclear factor κB (NF-κB) and activators of PPARα and PPARγ; thus, they have anti-inflammatory and anti-tumor properties." (PMID 36765904, 2023). "Treatment with caspase-1 inhibitors (YVAD, VADs, and NCX-4016) suppressed lipid accumulation and primary tumor growth for targeting the caspase-1/PPARγ/MCAD pathway in TAM differentiation." (PMID 37426676, 2023). "Given its involvement in several critical pathways that contribute significantly to tumor growth, progression, and metastasis, these findings provide additional evidence to support the potential targeting of PPARG for the treatment of ER+ BC." (PMID 37334066, 2023). "It has been shown that PPARγ is responsible for RSL3-induced ferroptosis, which leads to the obstruction of DC maturation, as PPARγ knockdown was sufficient to restore anti-tumor activity in RSL3 treated dendritic cells." (PMID 35954274, 2022). "The mRNAs of JUN, IL-6 and PPARG were reduced in tumor cells and up-regulated by Chidamide treatment." (PMID 36425653, 2022). "The PPARγ mRNA expression levels in tumor tissue were compared as a matter of different tumor features." (PMID 35922782, 2022). "WNT7a binds to FZD9 and signals to peroxisome proliferator activated receptor gamma (PPARγ) through an Erk5-dependent cascade, leading to anti-tumor signaling, including increasing epithelial and reducing mesenchymal gene expression." (PMID 35924166, 2022). "Among the three PPAR isoforms (PPARα, PPARβ/δ, PPARγ), PPARγ is the most studied to date due to its crucial role in carbohydrate and lipid homeostasis, regulation of apoptosis and tumor progression." (PMID 36499405, 2022). "In a xenograft model, researchers discovered that thalidomide reduced tumor development by 64%, and tumors in thalidomide-treated mice had higher expression of PPARγ than tumors in control mice." (PMID 35631448, 2022). "Among tumor- and pten-related genes, alpha-fetoprotein and PPARγ genes were reduced by probiotics treatment." (PMID 36171333, 2022). "Further scientific efforts are desirable to more precisely define the value of PPARg in the tumor-related context." (PMID 35406455, 2022). "In one study, PPARγ expression was markedly enhanced in the SM of tumor-bearing mice, which demonstrated the significance of the effect of PPARγ on muscle wasting." (PMID 35565236, 2022). "The tumor suppressor Cyld has been proposed as a transcriptional target gene of PPARγ in mammary epithelial cells." (PMID 35954274, 2022). "In accordance with these tumor-suppressive properties, we observed downregulation of PPARg in treatment-resistant as compared to naïve cells, whereas neither potential for survival prediction nor an association with histopathological findings was noted." (PMID 35406455, 2022). "In contrast to its overall anti-tumoral role in cancer cells, PPARγ governs major immuno-metabolic switches and alternative activation in immune cells, especially macrophages, thereby facilitating tumor initiation, progression, and metastasis." (PMID 35954274, 2022). "The PAX8/PPARG translocation results in a fusion protein that inhibits the tumour suppressor effects of PPARG." (PMID 35328664, 2022).